BRIP1 (BRCA1 interacting DNA helicase 1)
Diseases named in the same sentence as BRIP1 in open-access papers (continued):
Sharing a sentence is not in itself a finding about the gene and the disease.
breast cancer (continued). "Five rare variants in BRIP1/FANCJ, initially identified in ovarian cancer (OC) or breast cancer (BC) cases by the adult hereditary cancer clinics, were investigated for their candidacy as clinically relevant variants." (PMID 41596682, 2026). "For instance, heterozygosis in PALB2, BRIP1, and ATM increases the lifetime risk of breast cancer, while homozygosis causes multisystemic genetic syndromes, such as Fanconi’s anemia (PALB2 and BRIP1) and ataxia-telangiectasia (ATM)." (PMID 39858629, 2025). "The GEN1 gene is implicated in DNA damage repair, as are several high- or moderate-risk breast cancer susceptibility genes, i.e., BRCA1, BRCA2, PALB2, CHEK2, ATM, and BRIP1." (PMID 40649769, 2025). "A particularly interesting example is a BRIP1::VMP1 fusion in the MDA-MB-361 breast carcinoma cell line." (PMID 41421967, 2025). "Variants involving ATM, CHEK2, BRIP1, RAD51C, RAD51D, NBN and BARD1 are known to be associated with a moderately increased risk of breast cancer and a lifetime risk of around 25%." (PMID 38439815, 2024). "This economic evaluation estimates the cost-effectiveness of prevention strategies for ovarian and breast cancer among individuals with pathogenic variants in cancer susceptibility genes BRCA1, BRCA2, PALB2, RAD51C, RAD51D, and BRIP1." (PMID 38334999, 2024). "PVs in genes with moderate penetrance, such as ATM, CHEK2, BRIP1, and PALB2, double the risk of breast cancer." (PMID 39624521, 2024). "In this case, we describe the management of a male breast cancer patient with both BRCA2 and BRIP1 deleterious gene mutations." (PMID 38912178, 2024). "Subsequently, the following studies found BRIP1 promoting breast cancer cell invasion and migration." (PMID 36932143, 2023). "Distribution of VUS in breast cancer predisposing genes were :APC:1(5.8%), ATM:2(11.7%), BRCA1:1(5.8%), BRCA2:5(29.4%), BRIP1:1(5.8%), CDKN2A:1(5.8%), CHEK2:2(11.7%), FANC1:1(5.8%), MET:1(5.8%), STK11:1(5.8%), NF2:1(5.8%)." (PMID 37277882, 2023). "Higher expression of BRIP1 was noticed in brain and CNS cancer, breast cancer, cervical cancer, colorectal cancer, gastric cancer, head and neck cancer, pancreatic cancer, and sarcoma than in the corresponding normal tissues." (PMID 36907870, 2023). "In this regard, thequantitative assessment of Partner and localizer of BRCA2 (PALB2) and BRCA1Interacting Helicase 1 (BRIP1) genes expression in the breast cancer cell lineunder the treatment of Tamoxifen (TAM) was executed in this study." (PMID 39430039, 2023). "All other genes reported in this article except BRIP1 are now recommended for assessment of suspected hereditary breast cancer." (PMID 37563628, 2023). "Nevertheless, truncating variants in BARD1, BRIP1, and RAD51C are associated with a moderate risk of female BC, generally accounting for less than 1% of Breast Cancers." (PMID 35053526, 2022). "Several reports also demonstrated the existence of other genes at medium and low penetrance (e.g., BRIP1, RAD51C, RAD51D, BARD1, and PALB2), which have been associated with both Breast Cancer (BC) and OC risk." (PMID 35053526, 2022). "Other FA genes, such as FANCJ/BRIP1 and FANCN/PALB2, have also been identified as breast cancer susceptibility genes." (PMID 34830134, 2021).
breast cancer (continued). "One female breast cancer patient tested positive for PGVs in both BRIP1 and NF1, while one patient with splenic cancer harbored PGVs in both SDHB and BUB1B." (PMID 34830767, 2021). "Conversely, in two calycosin-treated breast cancer cell lines, an increase in ERα expression was offset by a decrease in BRIP1 expression, leading to inactivation of Akt and ERK1/2." (PMID 33647882, 2021). "Heterozygous variants in genes of the FA pathway, including BRIP1 and FANCA, have been described to predispose to breast cancer." (PMID 33840814, 2021). "Studies have found that BRIP1 can promote the invasion of breast cancer (BC) cells by regulating the expression of multiple downstream target genes, such as MGAT5, EPCAM, and CXCL12, especially in the triple-negative phenotype MDA-MB-231 cell line." (PMID 34408776, 2021). "Among them, CDKN2A showed a contribution to breast cancer risk that was comparable to that conferred by BRCA2, whereas RAD51C, RAD51D, BRIP1 were proven to be responsible for an increase in ovarian cancer risk." (PMID 31936873, 2020). "Breast and ovarian cancers are often linked to a genetic predisposition, most commonly through mutations in the breast cancer susceptibility genes BRCA1 and BRCA2, but also other genes, such as FANCJ/BRIP1, are associated with an increased disease risk." (PMID 32542039, 2020). "Homozygous mutations in BRIP1/FANCJ result in FA phenotype, while heterozygous truncating mutations are associated with a moderate risk of breast cancer." (PMID 31124294, 2019). "Mutations in other FA family members have been demonstrated to predispose to breast cancer, including PALB2 (FANCN), BRIP1 (FANCJ), RAD51C (FANCO), SLX4 (FANCP), and FANCM." (PMID 31320901, 2019). "They detected significant associations of some haplotypes of BABAM1, ATM, CTIP (RBBP8), TOPBP1, BRIP1, BRE and RAD50 with the modification of breast cancer risk." (PMID 30823486, 2019). "Among the hubs of the 6 modules, 5 of them (PTPN22, BRIP1, CEACAM6, LTF, and CCNT1) have been previously found to be associated with breast cancer, and the other one, MXRA5, has been reported to be related to non-small cell lung cancer." (PMID 30240439, 2018). "BRIP1 c.2392C > T (p.Arg798Ter) had a VUS and a pathogenic entry relative to phenotypes of breast cancer and Fanconi Anemia respectively, both contributed by the same submitter." (PMID 29308099, 2018). "Studies on TN breast cancer patients showed associations of breast cancer with mutations in moderate penetrance breast cancer susceptibility genes FALB2, BARD1, BRIP1, RAD51C, and RAD51D." (PMID 30249004, 2018). "Examination of the role of BRCA1 and BRCA2 in the DNA damage response has led to the identification of several breast cancer susceptibility genes such as FALB2, CHEK2, BRIP1, all of which interact directly or indirectly with BRCA1 or BRCA2." (PMID 30249004, 2018). "For example, women with inherited causative variant in the Fanconi anemia genes BRIP1 and PALB2 have a 20–50% lifetime risk of breast cancer." (PMID 29093764, 2017). "Together these results indicate that the overexpression of BRIP1 can contribute to breast cancer malignancy." (PMID 28317894, 2017).
breast cancer (continued). "BRIP1 gene is located on chromosome 17q22, just distal to the BRCA1 gene located at 17q21, a region that shows frequent loss of heterozygosity in breast cancers." (PMID 24040146, 2013). "BRIP1 encodes a protein that was identified as a binding partner of BRCA1 and was investigated as a breast cancer predisposing gene." (PMID 23586058, 2013). "Biallelic mutations of some of these hereditary breast cancer susceptibility genes, namely BRCA2/FANCD1, BRIP1/FANCJ, PALB2/FANCN and RAD51C/FANCO, have been identified in patients with Fanconi anemia (FA, [MIM 227650])." (PMID 23840564, 2013). "So far, while BRCA2, BRIP1, PALB2, and RAD51C are associated with high or moderate breast cancer risk, the impact of SLX4 on breast cancer remains to be measured." (PMID 22383991, 2012). "Some of the genes causing the Fanconi anemia (FA) syndrome, such as BRCA2, BRIP1, PALB2, and RAD51C, are associated with high or moderate risk of developing breast cancer." (PMID 22383991, 2012). "Subsequent studies reinforced this connection showing that truncating mono-allelic mutations in BRIP1/FANCJ and PALB2/FANCN had a frequency of approximately 1% in familial breast cancer cases." (PMID 22383991, 2012). "Breast cancer risk is also influenced by rarer variants that confer moderate breast cancer risks such as ATM, CHEK2, BRIP1 and PALB2." (PMID 20146796, 2010). "Mutations in ATM, BRIP1, PALB2, CHEK2 and possibly NBS1, RAD50 are also associated with a moderately increased risk for breast cancer, and many low penetrance genes have recently been identified." (PMID 18706089, 2008). "We sought to carry out mutation analysis of FANCD2, BRIP1/BACH1, LMO4 and SFN in a large number of non-BRCA1/2 breast cancer families." (PMID 16280053, 2005). "Deficiencies in the DNA damage repair pathway related genes constitute an important factor in the development of breast cancer, with approximately 10% of breast cancer cases being caused by mutations in HR genes, such as BRCA1, BRCA2, PALB2, BRIP1, BARD1, and RAD51C." (PMID 40830526, 2025). "How cost-effective are ovarian and breast cancer risk reduction strategies among women with pathogenic variants in individual cancer susceptibility genes (ie, BRCA1, BRCA2, PALB2, RAD51C, RAD51D, and BRIP1)?" (PMID 38334999, 2024). "Among breast cancer subtypes, the top eight mutational rates were MAD2L2/FANCV (37.5%), FANCI (32%), ATR (32%), FAAP20 (30%), FAAP100 (28%), SLX4 (27%), FANCT (27%), and BRIP1 (26%) in breast invasive carcinoma NOS." (PMID 39421870, 2024). "BRIP1 gene-related reports are related to breast cancer and ovarian cancer." (PMID 39211736, 2024). "Pathogenic variants (PVs) in BRCA1, BRCA2, PALB2, RAD51C, RAD51D, and BRIP1 cancer susceptibility genes (CSGs) confer an increased ovarian cancer (OC) risk, with BRCA1, BRCA2, PALB2, RAD51C, and RAD51D PVs also conferring an elevated breast cancer (BC) risk." (PMID 38334999, 2024). "Furthermore, the BRIP1 gene is known as a biomarkerfor breast cancer diagnosis and treatment monitoring." (PMID 39430039, 2023). "BRIP1 is not established as a risk factor of clinical relevance for breast cancer but has previously been shown to be associated with a moderate increased risk for ovarian cancer." (PMID 37563628, 2023).
breast cancer (continued). "The data show that there is a correlation between BRCA1 and BRIP1 in breast cancer patients." (PMID 36873936, 2023). "The National Comprehensive Cancer Network (NCCN) guidelines report on mutations in BRIP1 and RAD51C as being a cause for potential increase in breast cancer risk (specifically for triple negative breast cancers), but there is insufficient evidence for risk management." (PMID 35053526, 2022). "Moreover, the loss of function in DNA helicase genes including RECQL, BLM, WRN, RECQL5, and BRIP1 are also known to be highly correlated with the carcinogenesis of breast cancer and the BRCAness phenotype in breast cancer." (PMID 35855837, 2022). "In addition, more frequent, but less penetrant germline mutations have been identified in families with breast cancer in genes such as CHEK2, ATM, PALB2, and BRIP1." (PMID 35333900, 2022). "Variants of unknown/uncertain significance (VUS) in breast cancer susceptibility genes BRCA2, CHEK2 and BRIP1 were also identified in three different PABC patients (15%)." (PMID 34011307, 2021). "Other genes: Pathogenic variants in BRIP1, RAD51C, RAD50, NBN, STK11, and RECQL may also confer some level of breast cancer risk." (PMID 34439109, 2021). "We next determined the power of the competing RVAS tests to identify the 8 breast cancer risk genes (BRCA1-Missense, BRCA1-LoF, BRCA2-Missense, BRCA2-LoF, PALB2, BRIP1, CHEK2 and BARD1) at the three TIER levels 5%, 0.1% and 0.01% and at three levels of VE of 2%, 1% and 0.5% (Iberian: S6 Fig)." (PMID 33606672, 2021). "Other PVs were identified in genes that have a less clear association with breast cancer such as: BRIP1, NBN, RAD50 and RECQL, but none of these showed significant associations." (PMID 34439310, 2021). "Similarly to other genes such as BARD1, RAD51D, BRIP1, and RAD51C, FANCM is emerging as a breast cancer predisposing factor conferring a greater risk specifically for these breast cancer subtypes." (PMID 31991861, 2020). "The identified breast cancer susceptibility genes in the FA pathway, including BRCA1, BRCA2, BRIP1, PALB2, and RAD51C, are essential genes involved in HR, the error-free pathway for DSB repair during physiological cell cycle progression, which repairs replication-associated DNA damage." (PMID 32300589, 2020). "Although collagen type VIII alpha 1 chain (COL8A1) has been shown to be downregulated in BRIP1-knockdown breast cancer cells, its clinical role in breast cancer remains unknown." (PMID 32818022, 2020). "The opposite is seen for deleterious variants in BRIP1, with an increased risk of ovarian cancer but no increase in breast cancer risk." (PMID 33086730, 2020). "Up‐regulated BRIP1 levels in malignant breast tumours contradict its role as a tumour suppressor." (PMID 32888398, 2020). "While there is some evidence that truncating variants in BRIP1, especially p.Arg798Ter, are not substantially attributed to the development of breast cancer risk." (PMID 30975222, 2019). "There is no consensus on the role of truncating variants in BRIP1 in developing breast cancer, where no large systematic studies have been performed for providing clear evidence." (PMID 30975222, 2019). "Moreover, since many of the recruited high risk patients tested negative for BRCA1/2 mutations, it is plausible to take advantage of the collected DNA samples and test for mutations in other breast cancer susceptibility genes, e.g. CHEK2, PALB2 and BRIP1." (PMID 29409476, 2018). "Finally, among the breast cancer predisposition genes with moderate/high-penetrance, seven genes (BMPR1A, PTEN, CDH1, NF1, RAD51C, BRIP1, and CHEK2) were replicated for Korean BRCAX (eight for Asian and 15 genes for European high-risk breast cancers)." (PMID 30323354, 2018). "It has been reported that BRIP1 acts as a master regulator of breast cancer." (PMID 30240439, 2018). "Polymorphisms of BRIP1 is regarded as an important susceptibility factor in cervical cancer, but not in breast cancer." (PMID 29466248, 2018).
breast cancer (continued). "Interestingly, monoallelic mutations in some of the downstream proteins are known to confer a high risk of breast cancer (e.g., FANCD1 = BRCA2, FANCN = PALPB2, FANCJ = BRIP1, FANCO = RAD51C)." (PMID 26567103, 2014). "This is the case for mutations in the PALB2, BRIP1 and ATM genes, where heterozygotes have an increased lifetime risk of breast cancer, and homozygotes are diagnosed with multisystemic genetic syndromes (Fanconi’s anaemia for the first 2 genes and ataxia-telangiectasia for the latter)." (PMID 23570263, 2013). "Heterozygous mutations in FA genes have been associated previously with increased breast cancer risk, and, conversely, bi-allelic mutations in breast cancer-associated genes BRCA2, BRIP1, PALB2, and RAD51C have been identified in persons with FA or FA–like syndromes." (PMID 23028381, 2012). "Similarly, high mRNA expression of the BRCA1-interacting protein BACH1/Brip1 has been found in aggressive breast cancers." (PMID 19002265, 2008). "It has recently been established that mutations in two other FA genes may confer an increased risk of breast cancer; the increased risk for FANCJ/BRIP1 is around 2-fold, and that for FANCN/PALB2 is probably 2–4 fold, but may be higher for certain mutations." (PMID 18786261, 2008). "BACH1 (BRCA1-associated C-terminal helicase 1; also known as BRCA1-interacting protein 1, BRIP1) is a helicase protein that interacts in vivo with BRCA1, the protein product of one of the major genes for hereditary predisposition to breast cancer." (PMID 16430786, 2006). "We hypothesized that germline mutations in FANCD2, BRIP1/BACH1, LMO4 and SFN may account for some of the unexplained multiple-case breast cancer families." (PMID 16280053, 2005). "We therefore hypothesized that germline mutations in the BRCA1-interacting genes, FANCD2, BRIP1/BACH1, LMO4 and SFN, may account for some non-BRCA1/2 multiple-case breast cancer families." (PMID 16280053, 2005). "In addition, we screened a further 399 and 253 cases, respectively, for specific regions of the FANCD2 and BRIP1/BACH1 genes that contained functionally important domains, or variants previously found in the germline of breast cancer cases." (PMID 16280053, 2005). "Trials evaluating the benefit of PARP-inhibitors in breast cancer patients with mutations in HR-pathway genes other than BRCA1/2 have only included a very limited number of BRIP1-mutation patients and have not been able to confirm a PARP-inhibitor benefit for BRIP1-carriers." (PMID 40988318, 2025). "At present, BRIP1 germline modifications are not clearly associated with an increased risk for breast cancer; conversely, there is a strong association with ovarian cancer with an absolute lifetime risk up to 15% and risk-reducing surgery is recommended at 45–50 years of age." (PMID 38397209, 2024). "No data specifically connect BRIP1 mutations with BRCA2 breast cancer." (PMID 38912178, 2024). "Besides, evidence from the Kaplan-Meier plotter tool showed that high BRIP1 expression was associated with poor OS (P=0.026), PPS (post-progression survival) (P<0.01), and DMFS (distant metastasis-free survival) (P<0.001) prognosis for breast cancer." (PMID 36907870, 2023). "However, several of our premenopausal breast cancer patients carried germline variants of unknown/uncertain significance (VUSs) in eight different breast cancer susceptibility genes, namely BRCA1, BRCA2, CHEK2, RAD51C, RAD51D, ATM, BRIP1, and PMS2." (PMID 36011273, 2022). "Additionally, BRIP1 promotes cell proliferation and invasion in breast cancer." (PMID 36324591, 2022).